PDYN (prodynorphin)
Diseases named in the same sentence as PDYN in open-access papers (continued):
Sharing a sentence is not in itself a finding about the gene and the disease.
Depression (5 papers, 2014 to 2023). "The neuropeptides adrenomedullin, insulin-like growth factor 2, prodynorphin, and resistin were identified as mutually expressed in both periodontitis and depression, also playing a role in identifying depression." (PMID 37396968, 2023). "These postmortem studies had limited ability to conduct psychiatric state-based phenotyping to relate KOR or prodynorphin levels to depression severity." (PMID 34839360, 2021).
schizophrenia (4 papers, 2014 to 2023). A major psychotic disorder characterized by abnormalities in the perception or expression of reality. "Short tandem repeats and VNTRs in the cannabinoid receptor 1 (CNR1), glutamate ionotropic receptor NMDA type subunit 2A (GRIN2A), prodynorphin (PDYN), and proenkephalin (PENK) genes were reported to be associated with the vulnerability to schizophrenia and substance dependence." (PMID 35360861, 2022). "Ten patients with OCD exhibited significantly elevated serum autoantibodies to somatostatin and prodynorphin compared with 25 healthy controls and patients with advanced immunodeficiency virus (HIV), schizophrenia, Alzheimer’s disease, and multiple sclerosis." (PMID 37400462, 2023). "Other studies have reported an increase or no change in PDYN expression in postmortem brain in subjects with schizophrenia and other psychiatric disorders." (PMID 24405578, 2014).
spinocerebellar ataxia type 23 (4 papers, 2015 to 2021). Spinocerebellar ataxia type 23 (SCA23) is a very rare subtype of type I autosomal dominant cerebellar ataxia (ADCA type I). "Certain gene variants of PDYN have been associated to episodic memory performance and others have been shown to cause spinocerebellar ataxia type 23." (PMID 32576262, 2020). "Mutations in the prodynorphin gene (PDYN) are associated with the development of spinocerebellar ataxia type 23 (SCA23)." (PMID 34944698, 2021).
cocaine dependence (3 papers, 2013 to 2023). A psychologically and socially impaired state, with or without physiological changes, that develops as a result of using cocaine and which leads to compulsive behaviors to acquire the substance. "The risk haplotype is also associated with combined cocaine dependence and cocaine–alcohol co-dependence along with cocaine dependence, and likely enables low PDYN expression in the caudate and nucleus accumbens." (PMID 34200173, 2021). "In particular, one polymorphism affects an AP-1-binding site within the PDYN gene promoter, which may result in less PDYN transcription and an increased risk for cocaine dependence." (PMID 37938195, 2023).
mental disorder (3 papers, 2014 to 2022). A disease that has its basis in the disruption of mental process. "Prodynorphin (PDYN) is an endogenous agonist of the k-opioid receptors, having modulatory effects related to addiction; the expression of this peptide is altered in the brain of patients with mental disorders." (PMID 34721734, 2021).
neuropathy (3 papers, 2016 to 2020). A disorder affecting the nervous system that manifests with pain, tingling, numbness, and/or muscle weakness. "When tested over time, PDYN-KO mice developed slightly weaker neuropathy-induced mechanical hypersensitivity compared to wild-type animals, suggesting some pro-nociceptive tone of endogenous DYN." (PMID 27605249, 2016). "Altogether, we posit that the demonstrated changes in gene expression of the opioid propeptides and their respective receptors, i.e., PENK and DOP receptor vs. PDYN and KOP receptor, in neuropathy induced by sciatic nerve injury, may exert opposite influence on pain perception." (PMID 32026358, 2020).
substance dependence (3 papers, 2015 to 2022). The psychological or physiological need to take a substance in order to experience its effects or to avoid the effects of its absence. "Prodynorphin CpG dinucleotides that overlap with SNPs were differentially methylated in the dlPFC of postmortem brains from alcohol-dependent individuals suggesting a possible role for dynorphin in behaviors associated with substance dependency." (PMID 33192369, 2020). "Therefore, it is possible that these PDYN variants exhibit related sex-dependent effects across substance-dependence and related traits." (PMID 26502829, 2015).
alcohol use disorder (2 papers, 2015 to 2018). "Our findings expend contemporary knowledge by demonstrating that PDYN effects on alcohol use disorders differ between males and females, and this pattern of this difference appears to depend on phenotype." (PMID 26502829, 2015).
bipolar disorder (2 papers, 2020 to 2021). A disorder of the brain that causes unusual shifts in mood, energy, activity levels and the ability to carry out day-to-day tasks. "Consistent with the decreased levels of PDYN in DLB in our study, reduced dynorphin levels have also been observed in CSF from AD patients and in the amygdala of patients diagnosed with major depression and bipolar disorder." (PMID 32552841, 2020).
dementia (2 papers, 2012 to 2020). Loss of intellectual abilities interfering with an individual's social and occupational functions. "Knock-out of PDYN expression was suggested to protect against age related cognitive decline in mice, but its importance in human dementia is still unknown." (PMID 32576262, 2020).
heroin addiction (2 papers, 2018 to 2022). "The findings proposed that PDYN rs910080 variant significantly increased the risk of heroin dependence (CC vs TT: OR=7.91, 95%CI=3.36-18.61, P<0.0001)." (PMID 29911117, 2018). "In summary, our findings support an association between PDYN rs910080 variant and risk of heroin addiction in a sample of Iranian population." (PMID 29911117, 2018). "This study aims at investigating the effect of rs2281285, rs2235749, rs910080 and 68bp VNTR polymorphisms of prodynorphin (PDYN) gene on heroin dependence risk in a sample of the southeast Iranian population." (PMID 29911117, 2018). "The findings suggest that PDYN rs910080 T>C variant significantly increased the risk of heroin dependence." (PMID 29911117, 2018). "The findings showed that PDYN rs910080 T>C variant significantly increased the risk of heroin dependence (OR=7.91, 95%CI=3.36-18.61, P<0.0001, CC vs TT; OR=7.53, 95%CI=3.30-17.16, P<0.0001, CC vs TT+TC; OR=1.75, 95%CI=1.33-2.32, p<0.0001, C vs T)." (PMID 29911117, 2018). "Some studies evaluated the impact of PDYN polymorphisms on heroin dependence but, the available findings remained inconsistent." (PMID 29911117, 2018). "Altogether, our results provide an association between rs910080 polymorphism of PDYN gene and risk of heroin dependence in a sample of the southeast Iranian population." (PMID 29911117, 2018). "In the present study, we inspected the possible association between PDYN rs910080, rs2281285, rs2235749, and 68bp VNTR polymorphisms and heroin dependence in a sample of southeast Iranian population." (PMID 29911117, 2018).
Huntington disease (2 papers, 2022). Huntington disease (HD) is a rare neurodegenerative disorder of the central nervous system characterized by unwanted choreatic movements, behavioral and psychiatric disturbances and dementia. "Altered levels of CSF PDYN and/or PENK-derived peptides have been reported in Alzheimer’s disease (AD), frontotemporal dementia (FTD), dementia with Lewy bodies (DLB) and Huntington’s disease (HD)." (PMID 35216166, 2022).
malaria (2 papers, 2012 to 2024). Malaria is a serious and sometimes fatal disease caused by a parasite that commonly infects a certain type of mosquito which feeds on humans. "HDIs contain several candidate genes for local adaptation identified in previous studies, such as TRPV6, ASPM, prodynorphin [PDYN;], the duffy blood group locus involved in malaria resistance [DARC;], or the ectodysplasin A receptor [EDAR;]." (PMID 22439654, 2012).
methamphetamine dependence (2 papers, 2015 to 2018). A drug dependence that is a psychological dependency on the regular use of methamphetamine. "Several studies investigated the association between the PDYN VNTR polymorphism and susceptibility to heroin, cocaine and methamphetamine dependence." (PMID 27275252, 2015). "The aim of the present study is to investigate the association between PDYN VNTR polymorphism and methamphetamine dependence susceptibility." (PMID 27275252, 2015).
narcolepsy (2 papers, 2009 to 2020). A sleep disorder characterized by a tendency for excessive sleepiness during the day which occurs even after adequate sleep in the nighttime. "Interestingly, a substantial loss of hypothalamic cells producing hypocretin, PDYN and NPTX2 has been found in patients with narcolepsy." (PMID 32552841, 2020). "The overlap in symptoms might suggests a common etiology between DLB and narcolepsy and indicates that PDYN and NPTX2 reduction may be important biological substrates underlying sleep-related symptoms in DLB." (PMID 32552841, 2020).
Obesity (2 papers, 2023 to 2024). Accumulation of substantial excess body fat. "A novel potential regulator of β-cell function, Pdyn (Prodynorphin), is primarily expressed by a β-cell subpopulation associated with normoglycemic-obesity, while a genetic network associated with fatty acid metabolism is overexpressed in hyperglycemic-obesity." (PMID 36978008, 2023). "Chronically inhibiting PVN MC4R/PDYN neuron synaptic release by expressing tetanus toxin or ablating those neurons by expressing caspase-3 resulted in pronounced hyperphagia, obesity, and a significant elevation in food consumption." (PMID 38227343, 2024).
opioid dependence (2 papers, 2019 to 2022). "These peptides are ligands for the kappa opioid receptor (KOR), and an association has been shown between prodynorphin gene polymorphisms and opioid dependence susceptibility." (PMID 36362437, 2022). "Prodynorphin (PDYN) gene polymorphisms have been linked with opioid dependence (OD) with conflicting outcomes, the aim of this study is to synthesize the existing evidence of the association between PDYN polymorphisms and OD susceptibility." (PMID 31510971, 2019).
substance abuse (2 papers, 2014 to 2021). The use of a drug for a reason other than which it was intended or in a manner or in quantities other than directed. "In fact, it has been suggested that the OFC may play a role in the drug craving, and that genotypic variation of PDYN is associated with substance abuse and addiction." (PMID 24587148, 2014). "Some of us previously investigated involvement of eight genes in the opioid system (OPRD1, OPRK1, OPRL1, OPRM1, PDYN, PENK, PNOC, and POMC) and their potential effects on substance abuse." (PMID 34440333, 2021).
temporal lobe epilepsy (2 papers, 2011 to 2024). A localization-related (focal) form of epilepsy characterized by recurrent seizures that arise from foci within the temporal lobe, most commonly from its mesial aspect. "SIRPA is involved in negative regulation with numerous growth factor signaling receptors; and PDYN has been found to be associated with nonlesional temporal lobe epilepsy, but results have not been replicated." (PMID 21223598, 2011). "Limited to patients with temporal lobe epilepsy, we detected a significant correlation between the exponent and the cortical expression of GABRA1, GRIN2A, GABRD, GABRG2, KCNA2 and PDYN genes." (PMID 39056027, 2024).
Addison’s Disease (1 paper, 2019). "Unlike the CRF – CRF R1 receptor system where complete inactivation would produce Addison’s Disease-like symptoms, complete kappa-receptor inactivation does not affect viability (as demonstrated by the viability of prodynorphin or kappa receptor gene deletion)." (PMID 30787880, 2019).
Anorexia (1 paper, 2022). Lack of desire to eat (loss of appetite). "Recently, a study demonstrated that prodynorphin (Pdyn)-expressing PBN neurons receive information regarding mechanical stretching via the NTS, which mediates anorexia and negative valence." (PMID 35474336, 2022).
cardiac hypertrophy (1 paper, 2022). "Taken together with the data from the present study, PDYN appears to be a key candidate for further research in order to understand its potential involvement in the development of cardiac hypertrophy." (PMID 35207580, 2022).
celiac disease (1 paper, 2011). An autoimmune genetic disorder with an unknown pattern of inheritance that primarily affects the digestive tract. "In comparison with IgA, IgG was detected in the sera of celiac disease patients most prominently against TG, followed by prodynorphin, wheat extract, and then glutenin-21 mer." (PMID 23724236, 2011).
cognitive decline (1 paper, 2018). "In this framework, the decrease in PDYN expression in dlPFC may be interpreted as adaptation that may counteract cognitive decline developed over the years of heavy alcohol drinking and withdrawal." (PMID 29925858, 2018).
Cognitive impairment (1 paper, 2021). Abnormal cognition is characterized by deficits in thinking, reasoning, or remembering. "Consistently, it was hypothesized that the PDYN/KOR system is dysregulated in the dlPFC and hippocampus of alcoholics, and that these changes contribute to cognitive impairments." (PMID 34200173, 2021).
Crohn disease (1 paper, 2011). A gastrointestinal disorder characterized by chronic inflammation involving all layers of the intestinal wall, noncaseating granulomas affecting the intestinal wall and regional lymph nodes, and transmural fibrosis. "Differences between the mean ODs of IgA antibody against 3 out of 11 tested antigens in healthy controls versus patients with Crohn's disease were significant (P < 0.0035 for prodynorphin, P < 0.0044 for γ-gliadin-15, P < 0.0047 for TG)." (PMID 23724236, 2011). "In the sera of Crohn's disease patients, IgG reacted most against wheat and wheat germ agglutinin then transglutaminase, prodynorphin, α-, and γ-gliadin; IgA reacted foremost against prodynorphin then transglutaminase and α-gliadin." (PMID 23724236, 2011).
Dystonia (1 paper, 2021). An abnormally increased muscular tone that causes fixed abnormal postures. "The disturbance of the striatopallidal and striatonigral pathways resulted in abnormal behaviors and dystonia, accompanied by prodynorphin downregulation and preproenkephalin upregulation, suggesting the inhibition of the direct pathway and the activation of the indirect pathway." (PMID 34625569, 2021).
focal epilepsy (1 paper, 2019). A seizure caused by a localized disorder. "Highly purified and concentrated AAV vectors, 2 × 109 genomic particles (gp) coding for human pDyn (AAV‐pDyn), or non‐functional control vectors (AAV‐ΔGFP) were injected into the epileptogenic focus about 1 month after KA injection, when focal epilepsy had developed." (PMID 31486590, 2019).
Hyperreflexia (1 paper, 2010). Hyperreflexia is the presence of hyperactive stretch reflexes of the muscles. "The increased hyperreflexia in isolated spinal cord and the increased basal sensitivity to pain stimulation suggest that a potential reduction in NMDA currents in spinal cord neurons in daDREAM transgenic mice is compensated by the reduced inhibition due to the low expression of prodynorphin." (PMID 21167062, 2010).
periodontitis (1 paper, 2021). An acute or chronic inflammatory process that affects the tissues that surround and support the teeth. "The neuropeptide genes ADM, IGF2, PDYN, and RETN were intersected between periodontitis and MDD, and FOSB was a crosstalk gene related to these neuropeptides on the transcriptomic level." (PMID 34721734, 2021).
proteinopathies (1 paper, 2022). "Accordingly, decreased CSF PDYN levels have been also reported in HD and DLB —proteinopathies with a prominent striatal or cortico-striatal pathology." (PMID 35216166, 2022).
psoriasis (1 paper, 2021). An autoimmune condition characterized by red, well-delineated plaques with silvery scales that are usually on the extensor surfaces and scalp. "In psoriasis-affected skin, a 4.7-fold increase (p < 0.05) and in psoriasis non-involved skin an 8.0-fold increase (p < 0.001) in the expression of PDYN mRNA was detected when compared with healthy control skin." (PMID 34884858, 2021).
neurodegenerative disease (4 papers, 2020 to 2022). A disorder of the central nervous system characterized by gradual and progressive loss of neural tissue and neurologic function. "Dysregulated metabolism and altered cerebrospinal fluid (CSF) levels of PENK and PDYN have been described in several neurodegenerative diseases." (PMID 35216166, 2022). "Moreover, dysfunctions in the PDYN pathway appear to be involved in developing behavioral and sleep disorders in neurodegenerative disease." (PMID 35216166, 2022). "In the present study, we investigated, for the first time, the levels of the PDYN- and PENK-derived peptides in patients with sCJD to thereby provide new insights into the possible mechanisms underlying the dysregulation of brain opioids in neurodegenerative diseases." (PMID 35216166, 2022). "Accordingly, CSF PENK and PDYN were within the normal range in ALS and AD, two neurodegenerative diseases with lack or low degree of striatal dysfunction/atrophy." (PMID 35737109, 2022). "CSF levels of PDYN, SCG2 and VGF were lower in DLB compared to all related neurodegenerative diseases studied (p < 0.05)." (PMID 32552841, 2020). "The combination of VGF, SCG2 and PDYN best differentiated between DLB and related neurodegenerative diseases with acceptable specificity and sensitivity." (PMID 32552841, 2020).
cancer (1 paper, 2018). A tumor composed of atypical neoplastic, often pleomorphic cells that invade other tissues. "Presence of Pomc and Penk transcripts was detected in cancer supernatant-recruited neutrophils isolated from four male and Four female mice, but prodynorphin (Pdyn) was below the level of detection." (PMID 30405367, 2018).
neurological disorder (1 paper, 2022). "Dynorphins are prohormone opioid endogenous peptides derived from prodynorphin (PDYN), whose expression is altered in brain of drug/alcohol abusers and neurological disorder patients." (PMID 35024095, 2022).
PDYN also shares sentences with these, for which no sentence is quoted: infection (7 papers); Alzheimer disease (3); amyotrophic lateral sclerosis (2); Hypercalcemia (2); neuroblastoma (2); Ataxia (1); autosomal dominant cerebellar ataxia (1); complex partial seizures (1); deafness (1); dentatorubral-pallidoluysian atrophy (1); endocarditis (1); ethanol (1); Friedreich ataxia (1); frontotemporal dementia (1); Hepatitis B (1); hypophosphatemia (1); hypothyroidism (1); mesothelioma (1); mitochondrial disease (1); morphine dependence (1); multiple sclerosis (1); Niemann-Pick disease (1); optic atrophy (1); parasitemia (1); peripheral neuropathy (1); pneumonia (1); polycystic ovary syndrome (1); septicemia (1); Staphylococcus infections (1); status epilepticus (1).
A further 1 disease shares a sentence with PDYN in 1 paper.